SMAD3 (SMAD family member 3)
Diseases named in the same sentence as SMAD3 in open-access papers (continued):
Sharing a sentence is not in itself a finding about the gene and the disease.
colorectal cancer (continued). "Specifically, we found that a subgroup of seven genes – BIRC5, CYCS, FZD3, FZD8, MAPK9, SMAD3, and SOS1 – that belong to the KEGG colorectal cancer pathway showed significant association with risk of BCC." (PMID 27367190, 2016). "Smad3 phosphorylated at Ser-208/213 is located in the nucleus, whereas Smad2 phosphorylated at the corresponding sites (Ser-250/255) is detected in the cytoplasm in colorectal cancer specimens." (PMID 38569937, 2024). "Exosome could transmit circCOG2 to induce colorectal cancer metastasis through miR-1305/TGF-β2/SMAD3 axis." (PMID 37256443, 2024). "KINDLIN1 and SARA regulate the phosphorylation of Smad3 in colorectal cancer." (PMID 35096085, 2022). "An alteration in SMAD3 mRNA can be observed in all stages of colorectal cancer." (PMID 33036415, 2020). "Second, it is possible that we missed pathogenic germline variants in moderate penetrance colorectal cancer genes such as ATM, SMAD3, or high penetrance syndromes primarily associated with other cancers such as BRCA1 and BRCA2, which were not part of our panel." (PMID 31647837, 2019). "Moreover, in drug resistant colorectal cancer cells 5-flourouracil (5-FU) can stimulate Smad3, which is believed to contribute to drug resistance." (PMID 28061442, 2017). "As our results demonstrated that miR-1 regulated tumor glycolysis in colorectal cancer cells via inactivation by Smad3, we investigated whether Smad3 was required for miR-1-mediated inhibition of tumor glycolysis and proliferation." (PMID 28471448, 2017). "We further demonstrated that Smad3 was central to the effects of miR-1 in colorectal cancer cells, establishing a previously unappreciated mechanism by which the miR-1/Smad3/HIF-1α axis facilitates the Warburg effect to promote cancer progression in vitro and in vivo." (PMID 28471448, 2017). "Critical components of transforming growth factor β pathway signaling, along with related proteins SMAD2 and SMAD3; SMAD4 and SMAD2 are located on chromosome 18q, a frequent site of loss of heterozygosity in colorectal cancers; inactivated by homozygous deletion or mutation." (PMID 25713610, 2014). "In addition, our team suggested that LHPP protein might impede the metastasis of colorectal cancer by mediating the phosphorylation of Smad3 in TGF-β/Smad canonical pathway." (PMID 36376886, 2022). "Subsequently, colorectal cancer cells release TGF-β1 into the tumor microenvironment, where it activates the mothers against decapentaplegic homolog 3 (SMAD3) pathway in memory CD8+ T cells, ultimately impairing their antitumor activity." (PMID 40270603, 2025). "In colorectal cancer, LHPP inhibits the migration and invasion of cancer cells by suppressing the phosphorylation of Smad3 in the TGF-β pathway." (PMID 40240758, 2025). "SMAD3 plays a key role in the TGF-β signaling pathway, and its PTMs are significant in the progression of colorectal cancer." (PMID 40466864, 2025). "By marking m6A sites in flanking reverse complementary sequences, METTL3 induces circ1662 in colorectal cancer, which enhances colorectal cancer invasion and migration through YAP1 and SMAD3." (PMID 39550559, 2024). "This study showed that SMAD3, SMAD4, and their proteins were significantly underexpressed in colorectal cancer." (PMID 36969909, 2023). "Increasing miR-330 expression in human colorectal cancer cells was reported to induce apoptosis and suppresses cell viability and migration through inhibition of HMGA2 and Smad3 expression." (PMID 37077419, 2023). "LASP1 has been reported to be upregulated in colorectal cancer facilitating cell progression through the PI3K/AKT, TGF‐β/Smad3 signaling pathway." (PMID 33074595, 2020). "Studies have shown that inhibition of BAMBI expression in colorectal cancer can upregulate TGF-β signaling, leading to elevated levels of p-Smad2 and p-Smad3." (PMID 31186664, 2019).
colorectal cancer (continued). "We demonstrated that miR-1 suppressed aerobic glycolysis while Smad3 promoted it via its downstream effecter HIF-1α and glycolytic enzymes, including HK2, MCT4, in colorectal cancer." (PMID 28471448, 2017). "A recent study indicated that GDF15 promoted EMT and metastasis in colorectal cancer through binding to the TGF-β receptor to activate Smad2 and Smad3 pathways." (PMID 28199981, 2017). "In colorectal cancer, METTL3 promotes the expression of circ1662 by m6A modification of circ1662 through binding to its flanking strand, while circ1662 can regulate SMAD3 expression by accelerating the nuclear localization of YAP1, which ultimately promotes invasive metastasis of colorectal cancer." (PMID 39289775, 2024). "We stably introduced the CAGA12-dynGFP reporter in colorectal cancer organoids that did not harbor mutations in TGF-β signaling pathway components by lentiviral transduction and assessed the SMAD3-driven transcriptional response after TGF-β stimulation." (PMID 35626109, 2022). "Moreover, since other studies previously demonstrated that CEA interacts with the TGF-β receptor and induces proliferation in colorectal cancer cells, SMAD family member 3 (SMAD3) expression was evaluated as a downstream marker of the TGF-β receptor." (PMID 35433442, 2022). "Additionally, Kindlin-1 is required for colorectal cancer cell migration and invasion via activation of the TGF-β/Smad3 signaling pathway and EMT." (PMID 34814915, 2021). "Interestingly, recent literature data, obtained in solid tumors including colorectal carcinoma, have suggested that both IL-15/IL-15α axis and TGF-β/SMAD-3 pathway are also involved in determining the effectiveness of the anti-EGFR agent, cetuximab." (PMID 33916844, 2021). "A mechanism was established by which the miR-1/Smad3/HIF-1α axis facilitates the Warburg effect to promote CRC progression in vitro and in vivo, showing the potential role of miR-1 in molecular therapy of patients with advanced colorectal cancer." (PMID 32309224, 2020). "Differences in expression between carcinoma and normal mucosa, or differential miRNA expression by genotype, was associated with six SNPs, SMAD3 rs12708492, BMPR2 rs228545, and NFκB1 rs230510, SMAD3 rs2414937, NFκB1 rs3821958, and RUNX3 rs6672420 for colorectal cancer overall." (PMID 28061442, 2017). "In contrast to the findings in colorectal cancer, our data revealed a novel mechanism by which circEIF3I promoted SMAD3 delivery to EEs by directly binding to the SMAD3 MH2 domain, eventually enhancing the phosphorylation of SMAD3 by facilitating the recruitment of SMAD3 to internalized TGFβRI." (PMID 37689715, 2023).
diabetes (56 papers, 2009 to 2025). "These authors demonstrated that Smad3 deficient mice are protected from diet-induced obesity and diabetes." (PMID 38629073, 2024). "In this study, we demonstrated that transplantation of Smad3-deficient islets produced a better therapeutic effect on diabetes and diabetic kidney injury in STZ-induced diabetic mice and in db/db mice." (PMID 34987651, 2022). "In mice, β-cell-specific activation of Smad3 promotes apoptosis and loss of β-cell mass in association with β-cell dysfunction, glucose intolerance, and diabetes." (PMID 32170115, 2020). "Some studies have shown that the loss of Smad3 expression attenuates diabetes-induced early glomerular changes in Smad3-knockout diabetic mice." (PMID 30002389, 2018). "Several diabetes-related or inflammation-related genes are included in the TG-associated pathways, such as SMAD3, TGFB1, CDKN2B, and IL10." (PMID 26308950, 2015). "Diabetes may cause dysregulation of Smad3 and Tgfb, two crucial regulators of insulin gene transcription and β-cell function." (PMID 38884019, 2024). "This implies that Smad3 is pathogenic in diabetes and targeting Smad3 in β cells may represent a novel β cell or islet replacement therapy for diabetes." (PMID 34987651, 2022). "Mice with β-cell-specific constitutively-active TGF-β/Smad3 signaling display increased susceptibility to β-cell apoptosis, which is associated with glucose intolerance, β-cell dysfunction, reduced β-cell mass, and diabetes." (PMID 32170115, 2020). "Therefore, we hypothesize that Smad3-deficient islets may be a novel cell replacement therapy for diabetes." (PMID 34987651, 2022). "Lines of evidence demonstrated that Smad3 knockout mice protect mice from high-fat diet-induced obesity, diabetes, and insulin resistance." (PMID 37600712, 2023). "Our data showed a significant increase in TGF-β1 with further upregulation of phosphorylated SMAD2 and SMAD3 in diabetes, which was indicative of increased inflammation." (PMID 36829889, 2023). "Smad3 also plays a pivotal role in the regulation of β cell apoptosis in the conditions of diabetes or metabolic syndrome." (PMID 35327565, 2022). "Most importantly, our recent work showed the deletion of Smad3 completely prevents overt diabetes in db/db mice." (PMID 35327565, 2022). "Deletion of Smad3 protected against cardiac fibrosis under a number of conditions such as hypertension, myocardial infarction, and diabetes." (PMID 36313337, 2022). "C66 can partially alleviate diabetes-induced kidney fibrosis by reversing elevated p-Smad3 levels via downregulating miR-21." (PMID 35865316, 2022). "Under the conditions of high glucose and diabetes, miR-21 controls p-Smad3 (Ser423/425), EMT, and ECM deposition modulation through Smad7." (PMID 35865316, 2022). "Previous studies have shown that TGF-β/Smad3 plays an important role in promoting diet-induced diabetes." (PMID 33705353, 2021). "In contrast to Smad3 WT-db/db mice, whose inadequate β cell compensation ultimately led to the development of diabetes, the β cell proliferation and function in Smad3 KO-db/db mice were well sustained and the compensation was maintained through the lifetime." (PMID 33456576, 2021). "In another study it was shown that inhibition of the TGF‐β/Smad3 pathway in mice protected against diabetes mellitus during high‐fat–induced obesity." (PMID 33942489, 2021). "Akr1c18 and Ucp1 are decreased dramatically in both Smad3 WT and Smad3 KO‐ db/db, indicating they are critical in diabetes‐related renal injury." (PMID 33369170, 2021). "And in the study, we identified Smad3 signalling as a potential vital factor that links diabetes with aggravated ICH." (PMID 31922310, 2020).
diabetes (continued). "Phosphorylated Smad2 and Smad3 were observed in the glomerular and mesenchymal areas of patients with diabetes, suggesting the important roles of Smad2 and Smad3 in EMT." (PMID 32515466, 2020). "Smad3 is a downstream signaling molecule that mediates TGF-β signaling, and deficiency of Smad3 protects mice from HFD-induced obesity and diabetes through regulation of adipocyte differentiation, and glucose and lipid metabolism." (PMID 30485307, 2018). "All the data were obtained under a diabetic condition, indicating that TGF-β–Smad3 signaling modulates the phosphorylation of the Smad1 C-terminal and linker domains simultaneously in diabetes mellitus." (PMID 30002389, 2018). "A pharmacogenetic analysis using a genome‐wide approach in the ACCORD (Action to Control Cardiovascular Risk in Diabetes) trial identified HSD17B3, SMAD3, and IPO11 as genetic markers of fenofibrate response." (PMID 30371334, 2018). "The underlying mechanism is that the overactivated RAAS is inhibited, which reduce the transformation of fibroblasts into myofibroblasts, mediated by the activated TGF-β1/Smad3 pathway, thereby leading to reducing the collagen synthesis and improving the cardiac remodeling induced by diabetes." (PMID 38799171, 2024). "More specifically, deletion of Smad3 simultaneously improves pancreatic β cell function, apoptosis, and systemic insulin resistance with the consequence of eliminated overt diabetes in diabetic mouse models, revealing Smad3 as a key mediator and ideal therapeutic target for DM2." (PMID 38629073, 2024). "Doxycycline-inducible β cell-specific overexpression of dominant-negative Smad3 (Smad3DN) prevents HFD-induced diabetes by decreasing β cell apoptosis, while overexpression of constitutively active Smad3 (Smad3CA) exacerbates diabetes with an increase in β cell apoptosis." (PMID 35327565, 2022). "In vivo data proved that TgN-Sestrin2 mice with STZ-induced diabetes were protected from renal lesions, podocyte loss, podocyte phenotypic alterations, increased expression of apoptosis-associated proteins, oxidative stress, and TSP-1/TGF-β1/Smad3 activation." (PMID 35908070, 2022). "Thus, our results supported the notion that ADAM17 knockdown ameliorates cardiac fibrosis probably via TGF-β/Smad3 signaling in diabetes mice." (PMID 36313337, 2022). "Deletion of Smad3 simultaneously improves β cell function, apoptosis, and systemic insulin resistance with the consequence of eliminated overt diabetes in diabetic mouse models, revealing Smad3 as a key mediator and ideal therapeutic target for type-2 diabetes." (PMID 35327565, 2022). "Specifically, aggravated Smad3 signalling dependent mitochondrial and ATF4‐CHOP apoptosis pathways may be the underlying mechanism that link diabetes with aggravated ICH." (PMID 31922310, 2020). "This led us to the hypothesis that Smad3 activation may play a distinctive role in aggravated ICH injury in diabetes." (PMID 31922310, 2020). "It was also demonstrated TGF-β/Smad3 was activation in diabetic rats and inhibition of it could improve the diabetes." (PMID 31552773, 2019). "TGF-β/SMAD3 signaling pathway is important in regulating glucose and energy homeostasis and might play a role in the chronic complications of diabetes." (PMID 31083617, 2019). "Moreover, by confocal microscopy was observed that early diabetes induced nuclear translocation of p-Smad3 (red label) in proximal tubular cells compared to CTL group." (PMID 31557800, 2019). "Moreover, the reduction in the number of WT1-positive podocytes is alleviated in Smad3+/-;db/db mice compared with db/db mice, suggesting that Smad3 activation is involved in podocyte damage in diabetes mellitus." (PMID 31150422, 2019). "Diabetes-associated reduction in body weight was not shown in probucol-treated Smad3+/−; db/db mice." (PMID 30002389, 2018).
diabetes (continued). "Accordingly, the lower expression of Smad3 in B6-ob/ob islets as a consequence of the presence of Lefty1 could trigger beta-cell proliferation in this diabetes-resistant model." (PMID 26348837, 2015). "Diabetes-associated reduction in body weight was not shown in Smad3+/−; db/db mice." (PMID 30002389, 2018). "Phosphorylated SMAD2, SMAD3, and TAK1, and increased levels of TβRI and TβRII were observed in HG-cultured NRCFs and diabetes-stimulated CFs, whereas total SMAD2, SMAD3, and TAK1 were not changed." (PMID 41170186, 2025). "Smad3 is an important transcriptional factor of TGF-β signaling and has been shown to promote diabetes by inhibiting β cell proliferation." (PMID 34987651, 2022). "Several lines of evidence have revealed that diabetes-induced renal NLRP3 inflammasome activation, TGF-β1/Smad3 activation, and ECM protein accumulation were inhibited in NLRP3 knockout mice." (PMID 34504642, 2021). "In diabetic patients and rodent models of diabetes, continuous exposure of cells to high glucose has been found to increase TGF-β1 levels in the glomerular and tubular compartments of the kidney, and Smad3 activation was observed in these cells." (PMID 32017705, 2020). "The present system level network biology analysis from diabetes and obesity microarray expression datasets shows that the interaction across TGFBRII, SMAD3 and GCR along with FFA can induce vascular complications in diabetes." (PMID 19997558, 2009). "In summary, ADAM17 knockout reduced diabetes-induced collagen synthesis and ameliorated cardiac remodeling through the inhibition of RAAS overactivation when combined with eplerenone treatment, which reducing TGF-β1/Smad3 pathway activation-mediated CMT." (PMID 38799171, 2024). "Our recent work also found that deletion of Smad3 in db/db mice (Smad3KO-db/db) prevents the onset of overt diabetes without obesity, hyperglycemia, insulin resistance, and glucose intolerance." (PMID 34987651, 2022). "In diabetes, mice lacking Smad3 are protected against both renal and cardiac fibrosis in streptozotocin (STZ)‐induced type 1 diabetes and in obese diabetic mice." (PMID 33733577, 2021). "Our findings indicated that ADAM17 knockout could improve diabetes-induced cardiac dysfunction and remodeling through the inhibition of RAAS overactivation when combined with eplerenone treatment, which reduced TGF-β1/Smad3 pathway activation-mediated CMT." (PMID 38799171, 2024). "Thus, islet β cells lacking Smad3 provide a better therapy for diabetes and diabetic kidney disease." (PMID 36147472, 2022). "Indeed, Smad3 can be activated by both TGF-β-dependent and independent mechanisms including Ang II, advanced end products (AGE), and CRP under various disease conditions such as hypertension and diabetes 125-127." (PMID 33907513, 2021). "However, as Smad2 also plays an essential role in the glucose-stimulated release of insulin in β cells 16, targeting Smad3 but not upstream TGFBR1 in islets (β cells) may be more favorable for cell replacement treatment of diabetes." (PMID 34987651, 2022). "Notably, the elevated phosphorylated (p)‐Smad3 level in db/db ICH mice was more significant than that in the nondiabetic ICH mice, indicating that Smad3 signalling may play a distinctive role in ICH injury with diabetes." (PMID 31922310, 2020). "However, recent studies have found that Smad3, but not Smad2, mediates renal fibrosis under different disease conditions, including diabetes, and may play a more important role in the pathogenesis of DN." (PMID 26449625, 2015). "Our findings demonstrate that TGF-β/Smad3 signaling overexpression and renal fibrogenesis are not exclusive to the late stages of ESRD but are present in early stages of diabetes." (PMID 31557800, 2019).